SNORD23 (small nucleolar RNA, C/D box 23)
Synonyms: HBII-115
Gene: Small nucleolar RNA gene on chromosome 19 (47,755,853 to 47,755,962, forward strand). Ensembl gene ENSG00000221803.
Gene Ontology:
Biological process: RNA processing
Cellular component: nucleolus
Homologues: Orthologues: macaque SNORD23 (99% identical), mouse Snord23 (87% identical), pig SNORD23 (87% identical), rat Snord23 (87% identical), guinea pig SNORD23 (81% identical).